FUT2 (fucosyltransferase 2 (H blood group))
Diseases named in the same sentence as FUT2 in open-access papers (continued):
Sharing a sentence is not in itself a finding about the gene and the disease.
colon cancer (8 papers, 2014 to 2024). "Our model suggests that the dysregulated fucosylation of aging epithelial cells, caused by the imbalance of FUT2 and FUT8 expression, increases the risk of colon cancer in older adults." (PMID 38456503, 2024). "We observed that FUT2 knockout resulted in increased DSS-induced colon tumors and EMT in FUT2△IEC mice, indicating the inhibitory effects of FUT2 and α-1,2 fucosylation on the progression and metastasis of colorectal cancer." (PMID 36973740, 2023). "This study indicated that the decreased levels of Fut2 promoted colon cancer metastasis, which was similar to our results." (PMID 36739428, 2023). "Only one study reported that downregulating the transcription of caudal-type homeobox 2 (a tumor suppressor) resulted in a decrease in the transcription level of Fut2, thereby contributing to colon cancer cells metastasis." (PMID 36739428, 2023). "Especially, LewisB/Y was highly expressed in colon-like cell lines and significantly positively correlated with the gene expression of FUT2, which has previously shown to be increased in colon tumors." (PMID 35489554, 2022). "An in vitro experiment showed that the CDX2 gene is associated with the increase in sLex/a expression and suppression of FUT2 in colon cancer cells during EGF/bFGF-induced epithelial–mesenchymal transition (EMT)." (PMID 24941225, 2014). "In addition, overexpression of Fut2 inhibited cell proliferation, invasion and tumor metastasis in colon cancer cells, both in vivo and in vitro." (PMID 36739428, 2023). "AQP1, a Colton blood group antigen system gene, was reported to be associated with poor prognosis in colon cancer and lung adenocarcinoma, while seven of the fifteen genes were reported to be prognostic in one tumor type (GCNT2, FUT7, FUT3, FUT2, DARC, CR1 and BSG)." (PMID 35955933, 2022). "Intriguingly, the tumor-promoting FUT2 and FUT8 expression was highly expressed in tumor colon cE02, cE03, and cE06 epithelial subsets in aging colon tumor." (PMID 38456503, 2024). "Fut2 was overexpressed in SW480 and HCT116 cells in vitro to investigate its role in proliferation, migration and invasion of colon cancer cells." (PMID 36739428, 2023). "In contrast, a direct involvement of CDX2 in the regulation of FUT2, which revealed potential binding sites for CDX1 and CDX2 and is involved in the generation of LeY/B antigens, was shown in colon cancer cell lines HT29 and DLD-1." (PMID 30909444, 2019).
colorectal cancer (8 papers, 2022 to 2025). A primary or metastatic malignant neoplasm that affects the colon or rectum. "Furthermore, our previously study found that Fut2 deficiency in IECs promote colorectal cancer (CRC) progression in a dextran sulfate sodium/azoxymethane (DSS/AOM) mouse model." (PMID 38550777, 2024). "Our results are consistent with this finding and highlight the inhibitory effects of FUT2 on EMT in colorectal cancer." (PMID 36973740, 2023). "FUT2 is known to be involved in the pathogenesis of many diseases in human, including colorectal cancer, pancreatic cancer, prostate cancer, peptic ulcer, atrophic gastritis, diabetes, and coronary heart disease." (PMID 38066482, 2023). "Migration and invasion assays, EMT detection, nude mice peritoneal dissemination models and intestinal specific FUT2 knockout mice (FUT2△IEC mice) were used to investigate the effect of FUT2 on metastasis in colorectal cancer." (PMID 36973740, 2023). "FUT2 is an inhibitor of colorectal cancer metastasis which, when overexpressed, suppresses invasion and tumor dissemination in vitro and in vivo." (PMID 36973740, 2023). "Similar results were obtained in vivo: FUT2 overexpression reduced metastatic dissemination of colorectal cancer cells to the peritoneum and inhibited EMT in vivo." (PMID 36973740, 2023). "FUT2 overexpression in the colorectal cancer cell lines HCT116 and SW480 attenuated their migratory and invasive capacities." (PMID 36973740, 2023). "FUT2 has been shown to inhibit EndoMT in colorectal cancer, which may indicate that its elevation here in XFG patients may be correlated to the hypothesized increase of EndoMT occurring within the SC." (PMID 38287276, 2024). "The role and molecular mechanisms of FUT2 in colorectal cancer remain largely unclear." (PMID 36973740, 2023). "Thus, identifying the role and target proteins of FUT2 as well as gaining insight into their biological functions in colorectal cancer are worthwhile." (PMID 36973740, 2023). "FUT2 was significantly suppressed during the EGF- or bFGF-triggered EMT of colorectal cancer cells." (PMID 36973740, 2023). "Taken together, our results highlight the inhibitory potential of FUT2 in colorectal cancer." (PMID 36973740, 2023). "Overexpressing FUT2 reduced EMT in colorectal cancer cells, suggesting that α-1,2 fucosylation may inhibit EMT." (PMID 36973740, 2023). "To identify α-1,2 fucosylated proteins that could mediate the effects of FUT2 dysregulation on colorectal cancer, we performed a quantitative proteomics study of total protein and N-glycosylated TMT markers from colon tissues of mice in both groups (WT and FUT2△IEC mice)." (PMID 36973740, 2023). "Together, these observations suggest that FUT2 is a regulator of the EMT program and metastatic capacity in colorectal cancer cells." (PMID 36973740, 2023). "FUT2 knock-out mice (FUT2△IEC mice) develop AMO and DSS-induced tumors and promote EMT in colorectal cancers." (PMID 36973740, 2023). "In summary, our results demonstrate that FUT2-knockout mice develop more AMO- and DSS-induced tumors and exhibit greater colorectal cancer EMT." (PMID 36973740, 2023). "To examine the relationship between FUT2 and colorectal cancer (CRC), we performed bioinformatics analysis of FUT2 expression profiles in the TCGA database and found that FUT2 was significantly downregulated in CRC." (PMID 36973740, 2023). "FUT2-induced α-1,2 fucosylation impacts the ability of low-density lipoprotein receptor-related protein 1(LRP1) to suppress colorectal cancer invasion." (PMID 36973740, 2023). "However, the role of FUT2 in colorectal cancer (CRC) metastasis remains unclear." (PMID 36973740, 2023). "However, the role of changes in fucosylation induced by FUT2 in colorectal cancer remains unclear." (PMID 36973740, 2023).
colorectal cancer (continued). "Our study demonstrated that FUT2 induces α-1,2 fucosylation and inhibits the EMT and metastasis of colorectal cancer through LRP1 fucosylation, suggesting that FUT2 may serve as a therapeutic target for colorectal cancer." (PMID 36973740, 2023). "Overexpressing FUT2 reduced the EMT and invasion of colorectal cancer cells." (PMID 36973740, 2023). "Our study demonstrated that FUT2 induces α-1,2 fucosylation and inhibits EMT and metastasis of colorectal cancer through LRP1 fucosylation, suggesting that FUT2 may serve as a therapeutic target for colorectal cancer." (PMID 36973740, 2023).
lung adenocarcinoma (8 papers, 2017 to 2024). A carcinoma that arises from the lung and is characterized by the presence of malignant glandular epithelial cells. "Our previous study indicated that FUT2 suppresses the apoptosis of lung adenocarcinoma cells; however, the underlying mechanism is still unclear." (PMID 36552800, 2022). "Our previous studies showed that FUT2 is upregulated in lung adenocarcinoma tissues, is associated with poor survival, and plays an important role in the development of lung adenocarcinoma." (PMID 36552800, 2022). "Here, we showed that FUT2 was overexpressed in lung adenocarcinoma and was associated with the T stage of lung adenocarcinoma." (PMID 36552800, 2022). "ROC analysis revealed that FUT2 had a diagnostic value, providing evidence that FUT2 might be a potential biomarker for lung adenocarcinoma." (PMID 36552800, 2022). "Our results suggest that FUT2 may be associated with lung adenocarcinoma development and thus is a potential biomarker or/and therapeutic target in lung adenocarcinoma." (PMID 29228607, 2017). "Further functional assays showed that FUT2 regulated adenocarcinoma cell proliferation, migration and invasion, and apoptosis, which also affected the expression of migration-associated and apoptosis-associated proteins in lung adenocarcinoma cell lines." (PMID 29228607, 2017). "The present study further confirms that FUT2 serves as a positive regulator in lung adenocarcinoma development and highlights the role of FUT2 in the tumorigenesis of LUAD." (PMID 36552800, 2022). "Our previous studies showed that FUT2 can promote lung adenocarcinoma cell proliferation, migration, and invasion and functions as a negative regulator of apoptosis." (PMID 36552800, 2022). "Taken together, these findings provide a mechanistic understanding of how FUT2 mediated the crosstalk between autophagy and apoptosis, which determine lung cancer cell death and survival, leading to the progression of lung adenocarcinoma." (PMID 36552800, 2022). "Our previous studies showed that fucosyltransferase 2 (FUT2) is highly expressed in lung adenocarcinoma (LUAD) and plays a vital role in the tumorigenesis of LUAD." (PMID 36552800, 2022). "FUT2 initially induces autophagy by exerting a cytoprotective function to prevent apoptosis in lung adenocarcinoma cells." (PMID 36552800, 2022). "Here, we found that FUT2 was up-regulated and had an AUC (Area Under Curve) value of 0.964 in lung adenocarcinoma based on the TCGA dataset." (PMID 36552800, 2022). "Up-regulation of FUT2 has been observed in non-small cell lung cancer, lung adenocarcinoma, and small cell lung cancer." (PMID 34943992, 2021). "FUT2 was only slightly detectable in lung tissues by immunostaining, and increased expression of FUT2 was detected in all stages of lung adenocarcinoma tissues." (PMID 29228607, 2017). "This study provides the first demonstration that FUT2 is a positive regulator of tumor growth/survival, invasion and metastasis in lung adenocarcinoma, complementing its biological role in lung adenocarcinoma cells." (PMID 29228607, 2017). "A549 and H1299 cells were used to model the potential proliferative role of FUT2 silencing in lung adenocarcinoma." (PMID 29228607, 2017). "Our findings not only reveal the pathological role of FUT2 in lung adenocarcinoma, but also shed light on discovering promising prognostic factors and therapeutic leads to target lung adenocarcinoma." (PMID 29228607, 2017). "According to these findings, we deduce that FUT2 is a key factor in promoting progression of lung adenocarcinoma." (PMID 29228607, 2017).
lung adenocarcinoma (continued). "Collectively, these findings provide the role of FUT2 in lung adenocarcinoma development and suggest a potential biomarker or/and therapeutic target for lung adenocarcinoma." (PMID 29228607, 2017). "To explore the expression of FUT2 in lung adenocarcinoma patients, we performed immunohistochemical (IHC) staining on slides with lung adenocarcinoma tissue, including stage I, II and III." (PMID 29228607, 2017). "In the present study, rate of apoptosis of A549 cells could be increased by FUT2 knockdown, and the growth of A549 cells was inhibited, which means that FUT2 can promote lung adenocarcinoma development." (PMID 29228607, 2017). "Our in vitro findings shed light on how FUT2 promotes lung adenocarcinoma progression." (PMID 29228607, 2017). "This suggests that FUT2 knockdown suppresses the growth of xenografted lung adenocarcinoma tumors and that FUT2 might be involved in the development of lung adenocarcinoma in vivo." (PMID 29228607, 2017). "Together with the data, we propose that FUT2 is related to lung adenocarcinoma progression, and FUT2 might be a potential novel biomarker and therapeutic target for lung adenocarcinoma." (PMID 29228607, 2017). "Moreover, we demonstrated that knockdown of FUT2 inhibited cell proliferation, migration and invasion of lung adenocarcinoma cells, and restrained the tumorigenesis and development of lung adenocarcinoma." (PMID 29228607, 2017). "In this study, we found that the FUT2 was overexpressed in lung adenocarcinoma." (PMID 29228607, 2017). "The finding suggests that FUT2 promotes tumorigenicity and tumor growth in lung adenocarcinoma, although the pathological role of FUT2 remains largely unknown." (PMID 29228607, 2017). "In addition, FUT2 was upregulated and promoted cell migration and invasion in lung adenocarcinoma." (PMID 35899200, 2022). "In addition, we investigated the effect of knockdown FUT2 in lung adenocarcinoma cells." (PMID 29228607, 2017). "However, it’s still unclear whether the high expression level of FUT2 in lung adenocarcinoma is related to the clinical stage and pathological differentiation, and need further investigation." (PMID 29228607, 2017). "In lung adenocarcinoma (LUAD), it has also been reported that Fut2 promotes cancer metastasis through epithelial-mesenchymal transition initiated by TGF-β/Smad signaling." (PMID 36739428, 2023). "The study provides an integrated understanding of how FUT2 links autophagy and apoptosis in LUAD, which will be helpful for future diagnosis and therapy in lung adenocarcinoma." (PMID 36552800, 2022). "Compared to adjacent noncancerous tissue, the FUT2 expression was significantly increased in lung cancer (n=21) and lung adenocarcinoma tissues (n=15)." (PMID 29228607, 2017). "The results showed that the expression of FUT2 in lung adenocarcinoma is higher than that in adjacent noncancerous tissues." (PMID 29228607, 2017). "In addition, we found that FUT2 and FUT8 were overexpressed in lung adenocarcinoma." (PMID 29228607, 2017).
primary sclerosing cholangitis (7 papers, 2019 to 2025). "FUT2 SNPs were found to be genetic susceptibility factors for primary sclerosing cholangitis, a chronic cholestatic liver disease with progressive inflammation and fibrosis of the biliary tree." (PMID 40821120, 2025). "In addition, it was discovered in patients with primary sclerosing cholangitis that the FUT2 variant rs601338 correlated with CEA levels, particularly in patients genetically incapable of expressing CA19-9." (PMID 40821120, 2025). "By using large-scale genetic data, common variants of FUT2 have been identified to be associated with primary sclerosing cholangitis and concentrations of liver enzymes, which might be potential indicators for gallstones." (PMID 38529389, 2024). "Interestingly, previous studies have shown that in patients with primary sclerosing cholangitis, Fut2 non−secretors exhibit a different composition of bile microbiota compared to that of Fut2 secreters." (PMID 36838374, 2023). "The genotypes of FUT2 and FUT3 could also determine the cut-off values of CA19-9 for the detection of cholangiocarcinoma in patients with primary sclerosing cholangitis." (PMID 40821120, 2025). "Interestingly, previous research revealed that in patients with primary sclerosing cholangitis, Fut2 non-secretors exhibited a different composition of bile microbiota compared to Fut2 secretors." (PMID 33722220, 2021).
ulcerative colitis (7 papers, 2016 to 2025). An inflammatory bowel disease involving the mucosal surface of the large intestine and rectum. "In particular, minor alleles of FUT3 polymorphisms appear to increase susceptibility to ulcerative colitis, whereas minor alleles of FUT2 polymorphism are associated with increased susceptibility to celiac disease, as well as increased risks of Escherichia coli and Staphylococcus aureus infections." (PMID 32133503, 2020).
Obesity (6 papers, 2017 to 2025). Accumulation of substantial excess body fat. "FUT2 polymorphisms can influence the composition of gut microbes which in turn can cause both obesity and low B12." (PMID 34296321, 2021). "Thus, our finding that the G-allele of FUT2 rs602662 was associated with decreased levels of serum vitamin B12 as well as increased BMI, does not necessarily support a causal role of decreased vitamin B12 levels in obesity." (PMID 27995393, 2017). "If this could be translated to humans, in secretor positive pregnant women with either overweight or obesity, a downregulation of FUT2 before pregnancy could be a protective mechanism to counterbalance diet induced metabolic derangements." (PMID 38085123, 2024).
pancreatic cancer (6 papers, 2017 to 2025). "A previous cohort study has reported that the secretor phenotype, which was determined by single nucleotide polymorphism of FUT2, was not an effect modifier for the association between ABO blood group alleles and pancreatic cancer risk." (PMID 32232009, 2020).
hepatocellular carcinoma (5 papers, 2016 to 2025). A malignant tumor that arises from hepatocytes. "The expression of FUT2 was also downregulated by miR-15b and can facilitate the proliferation in hepatocellular carcinoma." (PMID 35899200, 2022). "The proliferation of hepatocellular carcinoma enhanced by Hepatitis B virus X protein was attributed to downregulation of microRNA-15b which resulted in upregulation of FUT2, leading to FUT2-induced Globo H expression." (PMID 30854233, 2019). "Indeed, FUT2-induced Globo H has been found to be increased by Hepatitis B virus X protein to enhance hepatocellular carcinoma proliferation." (PMID 30854233, 2019). "In this study, we examined the expression of their biosynthetic enzymes, FUT1, FUT2, B3GALT5 and ST3GAL2, in 135 hepatocellular carcinoma (HCC) tissues by qRT-PCR." (PMID 28883415, 2017).
osteoarthritis (5 papers, 2018 to 2023). A noninflammatory degenerative joint disease occurring chiefly in older persons, characterized by degeneration of the articular cartilage, hypertrophy of bone at the margins and changes in the synovial membrane. "It promotes arthritis progression via miR-17-5p/FUT2/β-catenin axis, and cartilage degradation in osteoarthritis by inhibiting WIF-1 expression and activating the Wnt pathway." (PMID 35626352, 2022). "For example, Huet al. found that HOTAIR promotes osteoarthritis progression through miR-17-5p/FUT2 signaling." (PMID 31481088, 2019).
celiac disease (4 papers, 2016 to 2021). An autoimmune genetic disorder with an unknown pattern of inheritance that primarily affects the digestive tract. "Therefore, alteration of the microbiota due to mutation of FUT2 gene decreases colonization resistance and has a role in the pathogenesis of celiac disease." (PMID 30158926, 2018). "Fut2-deficient mice presented more susceptibility to Candida albicans colonization comparing to wild-type mice and Candida albicans infection is a culprit in the onset of celiac disease." (PMID 30158926, 2018).
ear infection (3 papers, 2017 to 2021). A viral or bacterial infection that affects the external, middle, or inner ear. "The risk allele rs681343(C) (P = 3.51 × 10−30, OR = 1.11) is a synonymous mutation in FUT2 and is in almost complete LD with rs601338(G) (r2 = 0.9993), the ‘secretor’ (se) allele that is associated with higher risk of childhood ear infection in our data." (PMID 28928442, 2017). "The FUT2 stop variant c.461G>A (p.Trp154*; rs601338) has been associated with multiple mucosal phenotypes and is in strong linkage disequilibrium (LD) with a synonymous FUT2 variant rs681343 that was previously associated with childhood ear infections in genome-wide association studies (GWAS)." (PMID 35096646, 2021). "Although MAGENTA pathway analysis did not identify significant pathways of interest, variants in FUT2 and ABO, which are involved in the GSL biosynthesis pathway and were implicated in our mumps GWAS, were also significantly associated with childhood ear infection." (PMID 28928442, 2017).